SIRT1 (sirtuin 1)
Diseases named in the same sentence as SIRT1 in open-access papers (continued):
Sharing a sentence is not in itself a finding about the gene and the disease.
epilepsy (10 papers, 2017 to 2024). A brain disorder characterized by episodes of abnormally increased neuronal discharge resulting in transient episodes of sensory or motor neurological dysfunction, or psychic dysfunction. "Previous studies indicated that SIRT1 expression was increased in epileptic patients and experimental models of epilepsy within 1 h." (PMID 37880579, 2023). "Its inhibition has resulted in protective effects against epilepsy, reduced apoptosis and decreased activation of microglia and astrocyte by upregulating SIRT1." (PMID 35088379, 2022). "SIRT1 has been noted to be upregulated in patients with epilepsy and in rat models following acute seizure or status epilepticus." (PMID 31340436, 2019). "The beneficial effects of SIRT1 in terms of the mitochondrial energy supply and repair processes have given rise to the assumption that the up-regulation of SIRT1 by medium-chain fatty acids can play an important role in the treatment of drug-resistant epilepsies." (PMID 38892612, 2024). "The possible protective role of SIRT1 against the development of epileptogenesis and progression of epilepsy is related to different mechanisms including activation of autophagy and melioration of mitochondrial dysfunction which are induced by epilepsy." (PMID 37880579, 2023). "Activity of Sirt1 is increased in epilepsy patients and animal epilepsy models, suggesting that it could be involved in epileptogenesis." (PMID 33813634, 2021). "However, limited studies concerning the SIRT1 pathway in epilepsy and seizure-induced brain injury have been reported." (PMID 31340436, 2019). "Therefore, the SIRT1 can be considered as a target for potential neuroprotective strategies in epilepsy." (PMID 31340436, 2019). "Here, we examine the role of Sirt1 in the mechanism of insult-induced epilepsy development." (PMID 28197553, 2017). "Sirt1 is upregulated in epilepsy patients and after a proepileptic insult in rat models, yet a role for Sirt1 in seizure protection has also recently been suggested." (PMID 28197553, 2017). "Sirt1 was upregulated in epilepsy patients and increased in rat models of epilepsy within 1 h." (PMID 28197553, 2017). "Together, these data indicate that Sirt1 inhibitor administration immediately after the insult, although effective in blocking Sirt1 function, did not influence the development of a hyperexcitable network or of epilepsy within the 2 month time frame studied here." (PMID 28197553, 2017). "SIRT1 and BDNF have been identified as molecular targets of several miRNAs in the context of epilepsy." (PMID 35088379, 2022). "The ability to enhance SIRT1 signaling may provide new insights into the development of more effective neuroprotective strategies against seizure-induced brain damage, and the design of novel management perspectives against multiple drug-resistant forms of epilepsy and status epilepticus." (PMID 31340436, 2019). "The mechanism of activation of SIRT1 and PGC-1α during epilepsy or status epilepticus is unclear." (PMID 31340436, 2019). "In conclusion, blocking Sirt1 activity after KA-SE does not abrogate epilepsy development, suggesting that the mechanisms of such acquired epileptogenesis are independent of Sirt1 function." (PMID 28197553, 2017). "Blocking Sirt1 activity transiently after KA-SE did not significantly influence the time- course and all of the parameters of epilepsy development." (PMID 28197553, 2017). "Although the SIRT1 pathway is known to regulate PGC-1α/mitochondrial biogenesis and has been reported in various neurological conditions, at present, there is no report available on seizure disorders including status epilepticus." (PMID 31340436, 2019).
lupus nephritis (10 papers, 2014 to 2026). Glomerulonephritis in the context of systemic lupus erythematosus. "Our group has recently reported a strong association between the increased urinary levels of SIRT1 and histological features indicative of severity in lupus nephritis patients." (PMID 32887498, 2020). "RSV activated SIRT1, enhanced FcγRIIB expression, induced B-cell apoptosis, reduced serum autoantibodies and ameliorated lupus nephritis." (PMID 37483618, 2023). "However, SIRT1-null mice presented with immunoglobulin deposition in the kidneys as well as a high level of serum anti-nuclear antibody, which resembled the symptoms of lupus nephritis." (PMID 33981300, 2021). "Another Chinese herbal medicine named Honokiol (HNK) was capable of alleviating manifestation of the severe form of lupus nephritis (AFLN) by negative regulation of T cell functions and by enhancement of SIRT1/autophagy axis activation." (PMID 33981300, 2021). "Furthermore, LCF granule decreased p65 NF-κB levels and increased Sirt1 and Nrf2 levels in the kidney tissues of MRL/lpr mice, which might elucidate the beneficial effects of LCF on lupus nephritis." (PMID 27034698, 2016).
neuropathy (10 papers, 2018 to 2025). A disorder affecting the nervous system that manifests with pain, tingling, numbness, and/or muscle weakness. "Also, for the first time, we studied the SIRT1 variants in T2DM patients with neuropathy and retinopathy." (PMID 39474345, 2024). "Downregulation of SIRT1 in the spinal cord was also revealed in the paclitaxel-induced neuropathy model in the rat, similar to bortezomib-evoked neuropathy." (PMID 38138971, 2023). "Many of the processes in which VDR is involved, such as reduction of oxidative stress, neuroprotection, anti-inflammatory processes, and insulin control, are shared with SIRT1 and downregulation of both genes could contribute to the onset of neuropathy." (PMID 39976627, 2025). "The study detected a decreased expression of SIRT1 in the L4-L6 spinal dorsal horn in rats treated with BTZ, while in rats treated with BTZ and SITR1 activator resveratrol, an increase in SIRT1 expression and a significant reduction in the symptoms of neuropathy was observed." (PMID 35269574, 2022). "The present study also showed that SIRT1 was also involved in the painful neuropathy induced by chemotherapeutic drug bortezomib, as evidenced by our findings that recovery of SIRT1 activity with resveratrol attenuated the bortezomib-induced mechanical allodynia." (PMID 30342528, 2018). "In particular, stratifying subjects for the specific form of neuropathy, we observed that patients with CAN showed a significant decrease in SIRT1 expression levels (p = 0.037), also after correction by age, sex, duration, BMI and HbA1c (pcorr = 0.022)." (PMID 39976627, 2025).
progeria (10 papers, 2010 to 2024). "By contrast, miR-146a antagomir showed a similar role as metformin in recovering NAD+ level and SIRT1 activity in progeria mice." (PMID 35241643, 2022). "Importantly, SIRT1 activity decreases with age and treatment with the SIRT1 activator resveratrol improves aging pathologies in progeria mice, including adult stem cell decline." (PMID 32046343, 2020). "Because SIRT1 is able to delay premature senescence, it also plays a role in progeria." (PMID 26435834, 2015). "Furthermore, giving JH4 to LmnaG609G/G609G improved various progeria traits like body weight, cell density, grip strength, and organ size, extending their longevity.A new therapy for progeria has been proposed: resveratrol, a SIRT1 activator that interacts with lamin A." (PMID 36196312, 2022). "Next, the effect of miR-146a on AMPK-mediated SIRT1 activity and NAD+ level was evaluated in vivo using the D-gal-induced progeria mouse model." (PMID 35241643, 2022). "Interestingly, recent publications demonstrated an impact of SIRT1 on aging via NAD metabolism and age-related diseases like progeria." (PMID 37728850, 2024).
skin aging (10 papers, 2019 to 2025). The gradual irreversible changes in structure of skin that occur as a result of the passage of time.. "According to our results, GO-AGEs, individually and in combination with UVB irradiation, acted as deactivators of SIRT1, indicating its strong association with inflammation induced skin aging." (PMID 38246969, 2024). "Aquatide is a novel synthetic SIRT1 activator (heptasodium hexacarboxymethyl dipeptide-12) and modulates autophagy through SIRT1 activation, contributing to the suppression of skin aging caused by UV irradiation." (PMID 36278173, 2022). "Also, SIRT1 has been implicated in the modulation of inflammatory pathways and the promotion of antioxidant defenses, both of which are critical in counteracting the deleterious effects of skin aging." (PMID 40959178, 2025). "Three key skin aging-related CRGs, SIRT1, ARNTL, and ATF4, were identified based on machine learning." (PMID 37905958, 2023). "Based on bioinformatics and machine learning techniques, we obtained three key CRGs, SIRT1, ARNTL and ATF4, which are potential risk genes for skin aging and are also associated with the alteration of immune microenvironment in skin aging." (PMID 37905958, 2023). "Based on machine learning, we identified three key CRGs closely related to skin aging, namely SIRT1, ARNTL and ATF4." (PMID 37905958, 2023). "The aim of this review was to discuss the relevance of sirtuin 1 in skin aging, in the context of intrinsic factors, related to genetic premature aging syndromes, as well as extrinsic modifiable ones, with the assessment of its future application." (PMID 33917352, 2021). "The strong correlation between skin aging and sirtuin expression and extensive mechanistic studies have supported SIRT1 as a pharmacological target and resveratrol as a powerful prevention therapy of skin aging." (PMID 32456324, 2020). "So, treatments aiming at increasing SIRT1 activity or expression may demonstrate great potential for reducing skin aging." (PMID 40959178, 2025). "In this study, PDRN significantly upregulated SIRT1 expression at protein levels and attenuates stress granules in cytoplasm, particularly under UVB or H2O2 stimulation, implying PDRN could decrease skin aging by promoting the expression of SIRT1." (PMID 40343916, 2025). "Sirtuin 1 expression correlates with total fibroblast amount, and its proliferative activity and may be responsible for the development of skin aging symptoms." (PMID 33917352, 2021). "In conclusion, three key CRGs, including SIRT1, ARNTL, and ATF4, which are closely related to skin aging, were obtained based on bioinformatics and machine learning technology screening." (PMID 37905958, 2023). "Juglone, which up-regulates SIRT1 in skin cells, was also reported to play some protective roles against normal and UVB-induced skin aging." (PMID 31199782, 2019). "We further investigated the expression profiles of SIRT1, ARNTL and ATF4 in skin aging." (PMID 37905958, 2023).
acute lung injury (9 papers, 2018 to 2025). A condition of lung damage that is characterized by bilateral pulmonary infiltrates (pulmonary edema) rich in neutrophils, and in the absence of clinical heart failure. "Irisin reportedly improved the LPS-induced alveolar epithelial barrier dysfunction by activating AMPK/SIRT1 pathways in A549 cells and lung tissue of the acute lung injury mouse model." (PMID 33607992, 2021). "Administration of the selective SIRT1 inhibitor nicotinamide significantly reversed the protective effect of metformin against endothelial pyroptosis and lung injury in LPS-treated ECs and LPS-induced acute lung injury (ALI)." (PMID 35910360, 2022).
Cachexia (9 papers, 2008 to 2024). Severe weight loss, wasting of muscle, loss of appetite, and general debility related to a chronic disease. "To explore the molecular mechanism by which UA alleviates cachexia and prevents muscle wasting, we performed molecular docking on UA and SIRT1 protein." (PMID 37190306, 2023). "As seen in our investigation, NAMPT expression in the cachexia group was significantly increased with NR administration, whereas SIRT1 levels decreased." (PMID 34262449, 2021). "Interestingly, many of the cachexia associated genes such as FOXO1, FOXO3, SIRT1, SMAD3 and FABP3 were identified in age related gene expression in similar direction." (PMID 33923976, 2021). "In turn, the signaling axis, including SIRT1 and NOX4, may be a regulator of cellular senescence and oxidative stress, which may act as a cachexia regulator." (PMID 38334644, 2024). "Curiously, NR administration decreased SIRT1 expression, which was unexpectedly increased in the cachexia group, a contradictory finding, because of the lack of muscle regeneration during muscle wasting in tumor-bearing animals via SIRT1." (PMID 34262449, 2021).
cerebral infarction (9 papers, 2021 to 2025). An ischemic condition of the brain, producing a persistent focal neurological deficit in the area of distribution of the cerebral arteries. "For instance, lncRNA KCNQ1OT1 aggravates cerebral infarction by sponging miR-16-5p, leading to polypyrimidine tract binding protein 1 activation and subsequent SIRT1 downregulation in BMECs associated with inflammation and diminished angiogenesis." (PMID 39598406, 2024). "Resuvastatin may reduce cerebral infarction area and apoptosis rate in IS rats; the underlying mechanism may be related to SIRT1/NF-κB pathway regulation." (PMID 37627275, 2023). "Administration of astragaloside IV to mice promotes the expression of SIRT1 and activates the SIRT1/Mapt pathway, thereby inhibiting aberrant hyperphosphorylation and hyperacetylation of the microtubule-associated protein Tau, reducing cerebral infarction and rescuing neurological deficits." (PMID 36465185, 2022). "The upregulation of SIRT1 signaling can reduce the cerebral infarction volume and alleviate neurological deficits in MCAO/R mice." (PMID 40273147, 2025). "For example, miR-16-5p inhibition leads to downregulation of SIRT1 in BMECs, aggravating cerebral infarction." (PMID 39598406, 2024). "Preconditioning with a SIRT1 agonist can significantly reduce the area of cerebral infarction in mice with focal cerebral ischemia, and its mechanism is related to the downregulation of mitochondrial UCP2." (PMID 37627275, 2023). "In SIRT1−/− animals, the area of cerebral infarction was significantly increased following focal cerebral ischemia." (PMID 35528522, 2022). "It was found that artemisinin can improve cerebral infarction volume and oxidative stress damage by regulating the SIRT1/FOX1 signaling pathway, relieving CIRI, and then achieving the neuroprotective effect." (PMID 35422868, 2022). "SIRT1 gene overexpression significantly alleviated hippocampal damage, including less cerebral infarction, and reduced neuronal degeneration and cognition improvement." (PMID 35528522, 2022). "While compared with the AS-IV group, AS-IV + EX527 group showed higher mNSS scores (p < 0.05), more severe cerebral infarction (p < 0.05), lower SIRT1 expression (p < 0.01), and higher ac-MAPT and p-MAPT levels (p < 0.05)." (PMID 33841157, 2021). "Moreover, treatment with activator 3 (SIRT1 activator) can significantly reduce cerebral infarction volume in MCAO mice, possibly via inhibition of NF-κB induced inflammation and apoptosis pathways." (PMID 37627275, 2023). "In addition, HBO treatment also can increase the levels of ATP and NAD+ and consequently increase SIRT1 expression, leading to the attenuation of brain infarction volume, BBB integrity, and improvement of neurological functions in MCAO rats." (PMID 37627275, 2023). "After inhibiting SIRT1, the area of cerebral infarction increased at 7 days after reperfusion." (PMID 33841157, 2021). "Furthermore, MRI examination revealed an obvious brain infarction in rats treated with tMCAO and those treated with AAV-Empty at 3d after tMCAO, which was markedly diminished by SIRT1 overexpression but expanded by SIRT1 interference." (PMID 38767771, 2024).
cerebrovascular diseases (9 papers, 2018 to 2024). "Notably, individuals who are characterized by low SIRT1 levels early in life are prone to develop premature microvascular dysfunction during adulthood and display a higher risk of developing cardiovascular and cerebrovascular diseases." (PMID 36829935, 2023). "Nonetheless, there is a high interest in SIRT1-based vascular antiaging drugs for the treatment of cardiovascular and cerebrovascular diseases." (PMID 36829935, 2023). "As a key hub of steady-state cellular energy metabolism in the human body, SIRT1 is not only related to the occurrence of cardiovascular and cerebrovascular diseases, such as fatty liver, but also is closely related to the occurrence and development of PCOS." (PMID 36030228, 2022). "SIRT1 becomes a target for the prevention and treatment of age-related cardiovascular and cerebrovascular diseases since it has been confirmed to have important function on preventing vascular aging." (PMID 36238549, 2022). "Sirtuin 1 plays a crucial role in the development of vascular and cerebrovascular diseases." (PMID 38384936, 2024). "Fifth, conduct drug development and clinical trials based on the SIRT1-ER stress-NF-κB pathway to promote its application in the prevention and treatment of metabolic diseases, cardiovascular and cerebrovascular diseases, neurodegenerative diseases, and inflammatory diseases." (PMID 38745862, 2024). "However, Pgc1-α requires SIRT1 deacetylation to be fully activated.NF-κB is a master regulator of neuroinflammatory injury in cerebrovascular diseases." (PMID 36439686, 2022).
colorectal tumors (9 papers, 2006 to 2024). "We previously demonstrated that SIRT1 was upregulated in colorectal tumor cells deficient in glucose to promote the conversion of alternate energy sources." (PMID 37063423, 2023). "Our data suggested that SIRT1 plays a crucial role in the reprogramming of colorectal tumor cell metabolism and is an effective prognostic tool and a promising therapeutic target." (PMID 37063423, 2023). "In the present study, we identified sirtuin-1 (SIRT1) as the hub of the transformation of glucolipid metabolism in colorectal tumor cells." (PMID 37063423, 2023). "To ascertain the involvement of SIRT1 in FBXW11-mediated colorectal tumor growth, we co-transfected CRC cells with vectors carrying FBXW11 (or control vectors) and shRNA targeting SIRT1 (or scrambled shRNA sequence)." (PMID 34642302, 2021). "The immunohistochemistry staining revealed that the expressions of FBXW11 and SIRT1 in human colorectal tumors were positively correlated." (PMID 34642302, 2021). "However, using catalpol, a natural product with anticancer and epigenetic properties, leads to miR-34a upregulation, which suppresses the SIRT1/autophagy axis and triggers apoptosis in colorectal tumor cells." (PMID 39403142, 2024). "Our results, which indicate the existence of discrepancies between SIRT1 levels and activity in human colorectal tumors, may help to resolve the controversy." (PMID 37530744, 2023). "The involvement of HIC1 and SIRT1 during FBXW11-mediated colorectal tumor growth was also explored." (PMID 34642302, 2021). "Furthermore, the SIRT1 expression levels in colorectal tumor tissues may reflect the frequency of transition of glycolipid metabolism and serve as a therapeutic target and promising metabolic indicator of tumor progression." (PMID 37063423, 2023). "Chemotherapy can increase SIRT1/PGC1α-dependent OXPHOS in tumor cells, thereby promoting the survival of colorectal tumors during treatment." (PMID 39729352, 2024). "We used the HCT116 and DLD1 human colorectal tumor cell lines to perform a CRISPR/Cas9-based SIRT1 knockout (KO) and evaluate the correlation between SIRT1 and tumor growth." (PMID 37063423, 2023). "Colorectal cell lines showed SIRT1, EZH2, PCAF underexpression and SUV39H1 overexpression compared to colorectal tumours." (PMID 16638127, 2006).